SLC26A4 (solute carrier family 26 member 4)
Diseases named in the same sentence as SLC26A4 in open-access papers (continued):
Sharing a sentence is not in itself a finding about the gene and the disease.
deafness (continued). "In our previous study, two cases with heterozygous GJB2 mutations and two cases with homoplasmic 12S rRNA:A1555G mutations were identified from 92 Tibetan prelingual deafness students who underwent mutation screening for GJB2, SLC26A4, and mitochondria DNA 12S rRNA mutations." (PMID 25474651, 2014). "In addition to GJB2, SLC26A4 and MT-RNR1, a variety of less commonly screened deafness genes accounted for a significant portion of genetic causes of non-syndromic deafness." (PMID 23767834, 2013). "Even if those with variants of unknown significance are excluded, the heterozygote carriership rate for SLC26A4 mutations would be almost 4 times that for GJB2, the commonest form of inherited deafness." (PMID 23965030, 2013). "In the current study, we applied MLPA to screen for CNVs in a deafness-related gene, SLC26A4." (PMID 22551242, 2012). "Recessive SLC26A4 mutations are responsible for both non-syndromic hereditary hearing loss DFNB4 (MIM 600791) and Pendred syndrome (PS, MIM 274600), two disorders commonly encountered in patients with deafness." (PMID 21811566, 2011). "The total carrier frequency of deafness causing SLC26A4 mutations was 15.55% (21/135) in the case group and no SLC26A4 mutation was found in the control group." (PMID 23554706, 2011). "It has been proposed that Slc26a4−/− mice develop deafness via several mechanisms." (PMID 21811566, 2011). "GJB2 and SLC26A4 are the two most common etiologies for deafness in the Chinese population." (PMID 19744334, 2009). "Most reported studies focused on screening SLC26A4 mutations in the EVA or Pendred syndrome patients but not in the nonsyndromic deafness patients." (PMID 19040761, 2008). "Secondly, although the GJB2 and SLC26A4 genes are the major genetic causes of autosomal recessive non-syndromic deafness in the Chinese population, other related deafness genes that were not screened might have been missed." (PMID 38274112, 2023). "Of the 80 children with congenital bilateral hearing loss in the study, 59 (74%) were found to have genetic variants that may cause congenital deafness, including 44 with GJB2 or SLC26A4 gene variant, 1 with STRC gene variant, and 14 with other genetic variants that may cause deafness." (PMID 36142981, 2022). "Considering the patient’s congenital deafness and goiter, we did genetic testing on the patient and her daughters and identified compound heterozygous variations, exon 5-6 deletion, and NM_000441: c.2027 (exon 17)T>A, p.L676Q, in the SLC26A4 gene by whole exome sequencing." (PMID 36107570, 2022). "Notably, one infant with deafness-causative GJB2 c.235delC homozygous variant and one with SLC26A4 c.1229 C > T/c.1975G > C passed the two-step hearing screening in our study, while the remaining five individuals with homozygous or compound heterozygous variants failed both the hearing screenings." (PMID 36389375, 2022). "It has been reported that EVA might also be caused by the heterozygote of SLC26A4 and FOXI1, or double gene inheritance of SLC26A4 and KCNJ10, which is the first example where double gene inheritance has been proven to be the cause of deafness in human beings." (PMID 34276761, 2021). "It was suspected that variants in few genes like STRC, GJB2, SLC26A4, OTOG or TECTA may explain the hearing loss for the majority of individuals in our cohort as is the case in many other world populations for the individuals with moderate to severe deafness." (PMID 32681043, 2020). "The known deafness genes with variants detected in this study were GJB2 (MIM 121011; 21.2%), TMPRSS3 (MIM 605551; 6.1%), MYO15A (MIM 602666; 6.1%), TMC1 (MIM 606706; 3%), ADGRV1 (MIM 602851; 3%), PTPRQ (MIM 603317; 3%), SLC26A4 (MIM 605646; 3%), and OTOF (MIM 603681; 3%)." (PMID 31379920, 2019).
deafness (continued). "In summary, we proposed that PDS in this family could be a polygenic disorder which possibly arises from a combination of heterozygous mutations in SLC26A4, GJB2 and SCARB2 which associated with deafness, as well as compound heterozygous DUOX2 mutations which associated with thyroid dysfunction." (PMID 28222800, 2017). "Leading to Pendred syndrome, the most common form of syndromic deafness, as well as to DFNB4, a common form of non-syndromic deafness with enlarged vestibular aqueduct (EVA), mutations of SLC26A4 might be the second most frequent cause of hereditary hearing loss worldwide." (PMID 21811586, 2011). "Among these, a PCR hybridization screening group of 8276 neonates was tested for four deafness genes: GJB2, SLC26A4, mtDNA, and GJB3 by PCR hybridization." (PMID 38172182, 2024). "Four recessive (TRIOBP, SLC26A4, GJB2, COL4A3) and one dominant (SOX10) for the deafness; six recessive genes (LRGUK, DNAH9, ARMC4, DNAH2, RSPH6A, and ACE) for male infertility can be conclusively ascribed." (PMID 38884051, 2024). "Carrier screening for common deafness genes in the Chinese population, including the GJB2 and SLC26A4 genes, was performed using next-generation sequencing technology." (PMID 38274112, 2023). "In this study, preconception or prenatal carrier screening for the deafness genes GJB2 and SLC26A4 was performed in 9,993 individuals from China, with frequencies of 2.86% and 2.63%, respectively." (PMID 38274112, 2023). "In conclusion, this study performed preconception or prenatal carrier screening for the common deafness genes GJB2 and SLC26A4 in 9,993 individuals from China, showing carrier frequencies of 2.86% and 2.63%, respectively." (PMID 38274112, 2023). "Molecular epidemiological studies have found that the three common deafness genes GJB2, SLC26A4, and mtDNA 12S rRNA accounted for 30–50% of congenital HL." (PMID 35062939, 2022). "Molecular epidemiological studies have found several common deafness genes, such as GJB2, SLC26A4, and mitochondrial 12S rRNA, which appear to account for 30–50% of congenital hearing loss cases." (PMID 31541171, 2020). "Molecular epidemiological studies have found several common deafness genes in Chinese deafness population, such as GJB2, SLC26A4, and mtDNA12SrRNA." (PMID 32684921, 2020). "In our study, we have investigated the frequency of three common deafness‐related genes, GJB2, SLC26A4, and mtDNA 12S rRNA, in the patients with non‐syndromic hearing loss from Shanxi Province, an area with a high birth defect rate." (PMID 30693673, 2019). "On the one hand, common deafness-related genes such as GJB2 and SLC26A4 have minimal influence on the integrity of spiral ganglion neurons, leading to the speedy restoration of hearing after cochlear implantation." (PMID 26397989, 2015). "Three common deafness-related genes, GJB2, SLC26A4, and mtDNA12SrRNA, were analyzed using all-exon sequencing." (PMID 26252218, 2015). "Many deafness genes, including the well-known deafness genes GJB2 (MIM#121011), SLC26A4 (MIM#605646) and 12S rRNA (MIM#561000), have been identified." (PMID 25474651, 2014). "Five prominent deafness-related genes, GJB2, SLC26A4, GJB6, POU3F4, and mtDNA 12S rRNA, were analyzed." (PMID 22389666, 2012). "Fifteen variants in the SLC26A4 gene were identified in total in patients with EVA, two of which are novel; i.e., they are not yet present in available deafness databases or published literature (p.G139R, p.D754Ifs*5)." (PMID 40426046, 2025). "Here, we analyzed clinical and molecular data from 21 Chinese deaf families who did not have hotspot mutations in the common deafness genes GJB2, SLC26A4, GJB3, and MT‐RNR1." (PMID 33095980, 2020). "For the four deafness-related genes tested, including SLC26A4, GJB2, GJB3 and mtDNA 1555 and 1494, no pathological variants were found, indicating the origin of hearing loss from the pathological nature of GA-1." (PMID 33256818, 2020).
deafness (continued). "In our study, gene sequencing and analysis of deafness-related genes GJB2, GJB3, SLC26A4, and mtDNA did not reveal any mutation or SNPs in the patient and his mother." (PMID 31345197, 2019). "Gene sequencing and analysis of deafness-related genes GJB2, GJB3, SLC26A4, and mtDNA did not reveal any mutation or SNPs in the patient and his mother." (PMID 31345197, 2019). "We performed target region capture and next generation sequencing of 127 known deafness-related genes because the individual tested negative for hotspot variants in the GJB2, GJB3, SLC26A4, and MTRNR1 genes." (PMID 30068307, 2018). "In our cohort, the variant c.35delG was detected in homozygosity in two unrelated Caucasian patients with bilateral EVA and no SLC26A4 sequence alterations, and can reasonably be considered as the genetic determinant of deafness in these individuals." (PMID 29320412, 2018). "Thus, through this analysis, the molecular etiology of deafness was confirmed in 23.56% (90/382) of the patients, and it involved the GJB2, SLC26A4, CDH23, MYO15A, and MT-RNR1 genes." (PMID 27018795, 2016). "Furthermore, because of the extreme heterogeneities of causative genes, studies of molecular etiology have focused mainly upon deafness genes, such as, GJB2, SLC26A4, or OTOF, which make larger contributions to deafness in local populations." (PMID 25373420, 2014). "Overall, the clear contribution of GJB2, SLC26A4, and mitochondrial m.1555A > G to the etiology of the non-syndromic deafness population in south China was 32.0%." (PMID 24612839, 2014). "Three prominent deafness-related genes, GJB2, SLC26A4 and mtDNA 12S rRNA, were analyzed." (PMID 24341454, 2013). "Additional genotype-phenotype correlations report compound heterozygous SLC26A4 variants presenting with high frequency hearing loss and EVA (Mondini malformation) without goiter, manifesting more severe deafness, earlier age of onset, and more variable hearing levels." (PMID 40956475, 2025). "In addition, previous studies suggested that the sensitive period for successful CI outcomes for children with OTOF-related DFNB9 may be narrower than that for those with SLC26A4- and GJB2-related deafness." (PMID 32899707, 2020). "Another study used a comprehensive deafness gene panel (including 50 non-syndromic and 7 non-syndromic/syndromic deafness genes) to screen 125 deaf probands without common mutations in GJB2, SLC26A4, or MT-RNR1, and found potentially causative mutations in 26.4% (33/125) of the patients." (PMID 30682115, 2019). "Although many studies indicated that, similar to Western countries, mutations in GJB2, SLC26A4, and mtDNA 12S rRNA (MIM #561000) are the major cause of the genetic deafness in China, the molecular etiology of non‐syndromic deafness in the Chinese population has not been systematically investigated." (PMID 30693673, 2019). "Protein expression studies in SLC26A4 knockout mice have indicated that the absence of pendrin expression reduces KCNJ10 protein levels, supporting the hypothesis that deafness in the mouse model is secondary to loss of KCNJ10 function." (PMID 24860705, 2014). "Because Slc26a4-null mice have deafness but do not develop goiter, we fed the mutant mice a control diet or an iodine-deficient diet to evaluate whether iodine deficiency is a causative environmental factor for goiter development in PDS." (PMID 21689387, 2011). "In this study, we recruited 13 Chinese Han deafness families negative for GJB2, SLC26A4 and mitochondrial 12S rRNA." (PMID 36504663, 2022). "We recruited 13 Chinese Han deafness families who tested negative for GJB2, SLC26A4, and mitochondrial 12S rRNA." (PMID 36504663, 2022). "However, compared with non-genetic deafness, such as GJB2- or SLC26A4-related deafness, shows greater tolerance to delayed implantation, as late as up to 35 months after CI, as evidenced by better speech performance." (PMID 34097718, 2021).
hearing loss (156 papers, 2008 to 2026). "Genotype-phenotype correlations revealed that GJB2 variants were primarily associated with mild to moderate hearing loss, whereas SLC26A4 variants correlated with severe to profound phenotypes in the Singaporean populations." (PMID 41897287, 2026). "Thirty‐five children with GJB2 and SLC26A4‐associated hearing loss were identified by NGS (n = 27 GJB2‐HL; n = 8 SLC26A4‐HL)." (PMID 40008839, 2025). "Numerous studies have found thatthe prevalence of SLC26A4-associated hearing loss and thespectrum of pathogenic variants of this gene vary significantlyin different regions of the world." (PMID 40144368, 2025). "Dai P., Li Q., Huang D., Yuan Y., Kang D., Miller D.T., Shao H., Zhu Q.,He J., Yu F., Liu X., Han B., Yuan H., Platt O.S., Han D., Wu B.L.SLC26A4 c.919-2A>G varies among Chinese ethnic groups as acause of hearing loss." (PMID 40144368, 2025). "We formerly reported that SLC26A4 pathogenic variants are underrepresented in our Austrian cohort of patients with hearing loss and EVA compared to other Caucasian cohorts." (PMID 40121402, 2025). "Children with two pathogenic or likely pathogenic variants of GJB2 or SLC26A4 were considered to have genetic hearing loss." (PMID 40008839, 2025). "We identified several novel and rare SLC26A4 variants in patients with hearing loss from the Tyva and Altai Republics (Southern Siberia, Russia)." (PMID 41226768, 2025). "The obtained data are relevant both for predicting the prevalence of SLC26A4-caused hearing loss and for development of region-specific DNA diagnostics of inherited hearing loss in the Tyva Republic." (PMID 40144368, 2025). "In the present study, 57% of 35 children with GJB2 and SLC26A4 hearing loss were identified by newborn hearing screening with audiometric testing alone." (PMID 40008839, 2025). "Biallelic pathogenic SLC26A4 variants were detectedin 28.2 % (62 out of 220) of the patients included in the study.This rate of SLC26A4-associated hearing loss was one of thehighest among all populations in the world." (PMID 40144368, 2025). "We analyzed the haplotype structure for pathogenic variantsc.1545T>G and c.2027T>A of the SLC26A4 gene, found withhigh frequency in Tuvinian patients with hearing loss (theTyva Republic, Southern Siberia)." (PMID 40144368, 2025). "An additional 8 children with GJB2 or SLC26A4‐associated hearing loss passed their newborn hearing screen but showed hearing loss later; three of these children (38%) would have been identified by newborn genetic screening (3/6 GJB2‐HL; 0/2 SLC26A4‐HL)." (PMID 40008839, 2025). "Couple 185 had a child with hearing impairment, with genetic testing identifying the SLC26A4 variant c.919–2A>G (p.)?" (PMID 40421383, 2025). "The obtained data are relevantboth for predicting the prevalence of SLC26A4-associatedhearing loss and for developing region-specific DNAdiagnostics of inherited hearing loss in the Tyva Republic." (PMID 40144368, 2025). "Pathogenic variants in the SLC26A4 genelead to non-syndromic recessive hearing loss (type DFNB4)and Pendred Syndrome (OMIM #274600), a recessive diseasecharacterized by hearing loss and goiter." (PMID 40144368, 2025). "The provincial expanded Newborn Screening Program has good overlap with genetic findings in our clinical population with GJB2‐related hearing loss but captures only a small proportion of children in this region with variants in SLC26A4." (PMID 40008839, 2025). "Recessive variants of SLC26A4 are a common cause of hereditary hearing impairment and are responsible for non-syndromic enlarged vestibular aqueducts and Pendred syndrome." (PMID 40507794, 2025). "Danilchenko V.Y., Zytsar M.V., Maslova E.A., Bady-Khoo M.S.,Barashkov N.A., Morozov I.V., Bondar A.A., Posukh O.L. Differentrates of the SLC26A4-related hearing loss in two indigenous peoplesof southern Siberia (Russia)." (PMID 40144368, 2025).
hearing loss (continued). "The combination of genetic and physiologic hearing screening in newborns had the potential to increase identification rates from 57% to 66% in a cohort of children with GJB2 and SLC26A4 hearing loss." (PMID 40008839, 2025). "Here, we comprehensively reviewed the clinical characteristics of GJB2 and SLC26A4-related hearing loss, in addition to the physiological functions and pathogenesis of HL caused by mutations in these genes." (PMID 39609929, 2024). "This review contributes to providing a better understanding of the role of SLC26A4 and development of therapeutic approaches for the SLC26A4-associated hearing loss and SLC26A4-related dysfunction of various organs." (PMID 38673775, 2024). "Attempts to modulate SLC26A4 have occurred; however, an experimental approach has been proposed for hearing loss." (PMID 38673775, 2024). "Previous research demonstrated that there are hundreds of known variants in the SLC26A4 gene spreading over all exons and their flanking sequences associated with an increased risk of hearing loss." (PMID 38378613, 2024). "Most studies on SLC26A4 have focused on the relationship between hearing loss and SLC26A4 mutations and have been extensively reviewed elsewhere." (PMID 38673775, 2024). "In Section 5, although we summarized the physiological role of other organs than the ear, we suggest therapeutic approaches to recover expression of SLC26A4, which is mutated in SLC26A4-related hearing loss." (PMID 38673775, 2024). "A clinical trial of SLC26A4 mutation-induced hearing loss was suggested with a cochlear implant, whereas the studies of SLC26A4-related disease treatment are restricted to gene delivering therapy." (PMID 38673775, 2024). "Decreased presence or activity of human SLC26A4 at the plasma membrane is a common cause of hearing loss." (PMID 39383236, 2024). "In Korea and Japan, the c.919-2A>G appears to be the second-most common, by frequency, pathogenic SLC26A4 variant (after c.2168A>G (p.His723Arg)) in patients with hearing loss, and its frequency falls within 20–40% in Korea and 5–10% in Japan, respectively." (PMID 37107686, 2023). "We sought to identify changes in Slc26a4−/− mice to clarify cellular and molecular mechanisms underlying SLC26A4-related hearing loss." (PMID 37322474, 2023). "In our recent study, we revealed a high rate of the SLC26A4-related hearing loss in Tuvinian patients belonging to indigenous Siberian people living in Southern Siberia (Russia)." (PMID 37107686, 2023). "The study revealed that the SLC26A4 knockout mouse model exhibited a more pronounced auditory and inner ear phenotype compared to individuals with hearing loss associated with SLC26A4." (PMID 37928735, 2023). "At present, numerous studies aimed to investigate the prevalence of SLC26A4-related hearing loss, as well as the distribution of pathogenic SLC26A4 variants in various regions of the world." (PMID 37107686, 2023). "The presence of extracellular exosomes in SCs but their absence in IMCs and MCs suggests that abnormalities of SCs will be the primary causes of SLC26A4-related hearing loss." (PMID 37322474, 2023). "To identify the genetic cause of hearing loss, we performed WES in 373 families with hearing loss after prescreening for GJB2 and SLC26A4, the two most commonly mutated genes associated with hearing loss in Koreans." (PMID 37009795, 2023). "In particular, the proportion of c.919-2A>G, a well-known pathogenic variant, among other mutant alleles of the SLC26A4 gene found in different cohorts of patients with SLC26A4-related hearing loss, remains often uncertain." (PMID 37107686, 2023). "Biallelic mutations in SLC26A4 gene cause Pendred syndrome, characterized by sensorineural hearing loss, enlarged vestibular aqueduct, goiter, and variable CH." (PMID 36071330, 2023). "As a result, SLC26A4-related hearing loss is most commonly accompanied by the enlarged vestibular aqueduct (EVA) and/or other malformations of the inner ear structures." (PMID 37107686, 2023).